CD4 (CD4 molecule)
Diseases named in the same sentence as CD4 in open-access papers (continued):
Sharing a sentence is not in itself a finding about the gene and the disease.
diabetes (continued). "Another study pointed out that inhibition or downregulation of CatG in non-obese diabetic mice reduced the activation of CD4+ T cells, improved the function of insulin-secreting β cells in the pancreas, and slowed down the progress of diabetes." (PMID 34869231, 2021). "Treatment of BDC mice with αCD3 Ab (clone 2C11), a therapy shown to reverse diabetes in NOD mice, however, decreased expression of Foxo1-axis genes but increased expression of TCR-driven genes (Irf4, Nr4a1, Cd25, Cd69, Tbx21) in PLN BDC CD4+ T cells." (PMID 34314385, 2021). "Spontaneous diabetes was significantly delayed in YES-RIP-hB7.1 mice following transient treatment with depleting anti-CD4 and anti-CD8 monoclonal antibodies, leaving open the issue of the predominant role of either CD4+ or CD8+ T cells in our model." (PMID 34721418, 2021). "Interestingly, the gene targets of these miRNAs are enriched in CD56+ NK cells, whole blood, CD4+ T cells, CD8+ T cells, and pancreatic islet, indicating its potential role in diabetes and immune-related inflammation like periodontal diseases." (PMID 32756589, 2020). "People living with HIV and diabetes with thyroid disorders had lower CD4 counts than PLWHD without thyroid disorders (376.08 ± 333.30 vs. 509 ± 341.7 cells/mm3; p = 0.004)." (PMID 33240534, 2020). "Transfer of α4+/CD3+, but not α4+/CD4+ splenocytes from diabetic to NOD.α4-/- mice induced diabetes with short latency." (PMID 33291571, 2020). "Factors such as gender, physical inactivity, smoking, alcohol use, family history of diabetes mellitus, CD4 count, viral load, duration of HIV infection and old age have been shown to be responsible for the high prevalence of diabetes in such HIV-infected population." (PMID 32158504, 2020). "Compared with the euglycemia group, the CD3+ cell counts and the CD4+/CD8+ ratio were decreased, whereas the levels of IL-6 were increased in the secondary hyperglycemia group and diabetes group, with the diversities in the diabetes group being especially more significant." (PMID 33062712, 2020). "In diabetes studies in mice, CD127 blockage decreased T helper 1 (TH1) IFN-γ-producing CD4+ T cells in secondary lymphoid tissues and elevated PD-1 expression on autoreactive CD4+ T cells, limiting long-memory responses." (PMID 31507594, 2019). "Therefore, a relatively low Treg to effector CD4 cell ratio in NOD, compared to B6, mice is first observed shortly before the development of full-blown diabetes in our colony." (PMID 31281853, 2019). "Several risk factors have been shown to contribute to the high prevalence of diabetes in such HIV-infected population, including older age, male sex, family history of diabetes, duration of HIV infection, CD4 count, high body mass index, and hepatitis C virus (HCV) co-infection." (PMID 31262341, 2019). "Administration of IL-12, a key cytokine which guides the development of Th1 CD4+ T cells, induces rapid onset of insulin-dependent diabetes mellitus (IDDM) in the nonobese diabetic (NOD) mice, but not in BALB/c mice (With tendency of immune cells toward Th2)." (PMID 31030467, 2019). "The transgenic human CD4, expressed in addition to the murine orthologue, did not appear to be pivotal for diabetes development." (PMID 31612266, 2019). "However, significant decreases in this population were found at 9 weeks of age, i.e., at approximately the age that lower percentages of CD4+Foxp3+ cells are found in the periphery in NOD mice, and shortly before the mice begin to develop full-blown diabetes." (PMID 31281853, 2019). "Median CD4+ count was 483 cells/mm3 ([IQR]: 338, 682), 29% of persons had undetectable HIV viral load (HIV RNA < 80 copies/mL), 33% were on ART, 48% were hypertensive, 17% had diabetes, and 17% were co-infected with HCV." (PMID 30606136, 2019).
diabetes (continued). "Furthermore, PRL-expanded Treg (CD4+ Foxp3+) population and improved the efficacy of short-term low-dose anti-CD3 treatment (which induce a transient CD4+ and CD8+ T cell depletion) at achieving diabetes remission in the NOD mice." (PMID 29867762, 2018). "These cytokines play different roles in inflammatory states such as in diabetes; IFN-γ directs the differentiation of CD4+ lymphocytes into helper lymphocytes type 1 (Th1); it also intervenes in the activation of macrophages and induces a greater secretion of IL-12." (PMID 29805810, 2018). "Using a CD4+ T cell-mediated adoptive transfer model of autoimmune diabetes we observed that even though diabetes does not develop in recipient mice lacking IFNγ receptors, mice with MHC class II-deficient IEC were not protected from disease." (PMID 30555479, 2018). "In order to address whether the neuromuscular syndrome observed in ICOSL−/− NOD mice was dependent on both CD4+ and CD8+ T-cells, as seen for diabetes, or on either of these two subsets, we performed adoptive transfer experiments." (PMID 28424681, 2017). "Both CD4+ and CD8+ T-cells are involved in diabetes development and both major histocompatibility complex (MHC) class I- and class II-knockout NOD mice fail to develop diabetes." (PMID 28424681, 2017). "CD4 T cells are required for diabetes development in NOD mice, and either depletion of CD4 T cells or treatment with non-depleting anti-CD4 antibodies prevents diabetes." (PMID 29259578, 2017). "In human T1D, the available evidence from studies of individual islets from the Network for Pancreatic Organ Donors with Diabetes suggests that beta cell destruction is mediated in large part through direct CD8 T cell contact with beta cells and CD4 T cell-mediated polarization of M1 macrophages." (PMID 29259578, 2017). "CD8+ T-cells and CD4+ T-cells from aging conventional or ICOSL+/+ NOD mice directly transfer diabetes into NOD.scid recipients without the need of prior in vitro activation." (PMID 28424681, 2017). "CD8+ T cells deprived of continued CD4 help specifically in the pancreas, through blocking MHC class II recognition, failed to maintain optimal effector functions, which contributed to hamper diabetes progression." (PMID 29403481, 2017). "To investigate the expression of Programmed death-1 (PD-1) on T lymphocytes in patients with type 2 diabetes mellitus (T2DM) and severe sepsis, we determined PD-1 expression on CD4+ and CD8+ T lymphocytes of patients with T2DM, severe sepsis, and T2DM combined with severe sepsis." (PMID 27459386, 2016). "Second, they are inducers of apoptosis in effector T cells and thirdly they are able to induce allo- and autoantigen-specific Treg from naïve CD4+ T cells, which were able to block diabetes in a non-obese diabetes animal model." (PMID 26941742, 2016). "We showed that a ppinsΔA12-21 antigen (lacking the critical Kb/A12-21 epitope) primed regulatory T cells with a TGF-β+ Foxp3+ CD25+ CD4+ signature and efficiently suppressed CD8+ T cell-mediated diabetes development by a subsequent injection of the diabetogenic pCI/ppins vector." (PMID 27406624, 2016). "PD-1/PD-L1 deficiency on a diabetes-prone background (NOD) led to accelerated disease as previously reported, and increased numbers of insulin-specific but not foreign antigen-specific CD4+ T cells in the SLO and pancreas." (PMID 27656680, 2016). "We assessed the effects of increasing levels of IC87114 on T cells from diabetes-prone NOD mice in in vitro culture, looking at anti-CD3 and anti-CD28 induced proliferation of CD4+ T cells (left hand panel) and CD8+ T cells (right hand panel) and production of IFN-γ." (PMID 26783747, 2016). "The advanced age, late presentation, systemic inflammatory response syndrome on admission, diabetes mellitus, extension of infection to the abdominal wall, high Fournier’s gangrene severity score (>9) and HIV infection with low CD4 count (<200 μl/cells) were the main prognostic factors of mortality." (PMID 26416258, 2015).
diabetes (continued). "Known risk factors for CKD among HIV-positive patients are black race, older age, CD4 count <200 cells/mm3, HIV RNA levels >4,000 copies/ml, family history of renal disease, clinical progression to AIDS, diabetes mellitus, hypertension, and co-infection with hepatitis B (HBV) or Hepatitis C (HCV)." (PMID 26317657, 2015). "Understanding the mechanisms by which CD4+CD25+ cells exert their influence during IBDV infection can give us implications for the development of therapeutic strategies for many other diseases including cancer, diabetes, and immune mediated diseases." (PMID 25803101, 2015). "In the univariate analysis, age, diabetes, hypertension, hyperlipidemia, hepatitis C, time since the HIV diagnosis, opportunistic diseases, current CD4+ count, indinavir exposure, and past and current exposure to TDF and ATV⋁LPV were significantly and positively associated with the primary outcome." (PMID 24699873, 2014). "All-trans retinoic acid treatment inhibited diabetes in NOD mice with established insulitis by the expansion of Treg cells that suppressed IFN-γ-producing CD4+ and CD8+ T-cells, without affecting Th17 cells or IL-4 producing cells." (PMID 23970886, 2013). "In fact, PC61 administration to adult NOD mice has also been reported to delay diabetes onset, perhaps due to its negative impact on activated CD4+ and CD8+ T effector cells with upregulated CD25 expression." (PMID 23691523, 2013). "In addition, depletion of CD4+CD25+ Treg impaired the inhibitory effect of ATRA on islet-infiltrating CD8+ T-cells and blocked its protective effect on diabetes." (PMID 23970886, 2013). "As in previous studies, we interrogated the transcriptome analysis of spleen since it is the major site of immune responses and contains both T-cells capable of transferring diabetes into immunodeficient NOD.scid mice and macrophages that act as effectors of CD4+ T-cell mediated T1D." (PMID 23383062, 2013). "Diabetes transferred to NOD-SCID mice by BDC2.5 or NtfrRII specific CD4+ T-cells can be prevented by B but not T-cells from scFv-vaccinated donor mice if the specificity of the vaccine scFv and the specificity of the inducer cells are matched." (PMID 23894487, 2013). "This could lead to upregulation of CD4+ CD25+ Foxp3+ regulatory T cells, the process connected with autoimmune nature of diabetes mellitus." (PMID 24069226, 2013). "Diabetes did not affect the changes in the level of white blood cells and CD4 counts, and this was not modified by HIV status (data not shown)." (PMID 22839693, 2012). "Ten days post-implantation, a time at which recurrent diabetes is first detected, TCR Vβ usage by CD4+ and CD8+ naïve and Teff/mem was examined in the islet graft, the renal lymph node (RLN) draining the graft site, pancreas, pancreatic lymph node (PLN), and spleen of individual recipients." (PMID 23251685, 2012). "Therefore, we determined miR-10a expression levels in diabetes-prone NOD and autoimmune-resistant B6 Treg cells (CD4+CD25+CD62Lhi)." (PMID 22629323, 2012). "Non-genetic variables such us diabetes mellitus, hypertension, and CD4+ T cell count at HIV-infected diagnosis reached significance in the logistic regression analysis." (PMID 23230442, 2012). "The vitamin D deficiency was observed regardless of age, sex, BMI, dyslipidemia, diabetes, hepatitis B or C coinfection, current CD4 cell count, current HIV-1 RNA load, time of exposure to ART, and use of protease inhibitors." (PMID 24052874, 2012). "At this time, particularly given the promising results with non-depleting anti-CD3 in early onset diabetes patients, the past experience of anti-CD4 in human patients should be reassessed in face of current knowledge." (PMID 21818308, 2011). "In the T1D NOD mouse model, it has been shown that the pool of CD4+CD25+ regulatory T cells decreases with the progression of diabetes and that administration of these cells affords protection against the development of diabetes." (PMID 21647403, 2011).
diabetes (continued). "Thus, 4–6 wk old NOD mice were injected with 1−3×106 CD4+CD25+ T cells and subsequently monitored for diabetes." (PMID 19759824, 2009). "Consistent with a previous report, our results showed that high numbers of these CD4+CD25+ T cells (6×106) were insufficient to prevent diabetes (data not shown)." (PMID 19759824, 2009). "In non-immunosuppressed recipients, islet xenografts reverse diabetes but the majority of transplanted xenogenic islets are subjected to acute cellular rejection mediated by CD4+ and CD8+ T cells and macrophages." (PMID 19617916, 2009). "Using a novel class II MHC tetramer, we have isolated a population of CD4+ Foxp3− T cells specific for the autoantigen glutamic acid decarboxylase p286–300 peptide (NR286 T cells) from diabetes-resistant non-obese resistant (NOR) mice." (PMID 19924236, 2009). "Our study suggests, for the first time, that CD4+CD25+ regulatory T cells may play an important role in the control of diabetogenic cells and prevention of diabetes development in CFA-treated disease-free NOD mice." (PMID 19011680, 2008). "The findings revealed significant gender differences in gene expression and abundance of CD4+ cells, with the transcriptome of Peripheral Blood Mononuclear Cells (PBMCs) reflecting CAD and diabetes mellitus (DM)." (PMID 38263066, 2024). "When assessing the influence of comorbidities on the immune response after two doses of anti-SARS-CoV-2 mRNA vaccine in dialysis patients, the results showed no significant relation between diabetes, malignancy and antibody production, levels of CD4+, CD8+ cells." (PMID 38792691, 2024). "Furthermore, recirculating clones of PD-1+CD4 Tconv cells showed lower expansion in obese VAT regardless of diabetes status, suggesting that they likely undergo bystander cytokine-mediated activation." (PMID 38380252, 2024). "Although the CD4+ cell count was highest in the diabetes group, this increase was not significant." (PMID 39479688, 2024). "Notably, the VAT of obese patients showed a trend of enrichment in CD4 Tconv public clonotypes compared to LC, regardless of PD-1 expression or diabetes status." (PMID 38380252, 2024). "In contrast, Tregs reduced the incidence of diabetes compared with mice receiving no CD4+ T cells." (PMID 36705564, 2023). "Likewise, splenic tetramer+ (but not tetramer−) CD4+ T cells from BDC2.5 mi/I-Ag7-NP-treated donors suppressed diabetes development in T-cell-reconstituted NOD.Scid hosts." (PMID 36973489, 2023). "Overall, these results demonstrated continuous CD4+ and CD8+ T cell trafficking between the pancreas and its draining lymph nodes during disease progression and massive T cell accumulation in late-stage pre-symptomatic diabetes, which was reflected by increased circulating T cell numbers." (PMID 38027120, 2023). "Furthermore, the frequencies and absolute numbers of FoxP3+ Treg in the SILP were markedly lower in antibiotics-treated animals compared to non-treated mice with MLDS-induced diabetes, as well as the proportion of CD4+ T cells." (PMID 37110604, 2023). "Risk factors for kidney disease in PWH are older age, black race, higher viral loads, low CD4 cell counts, chronic use of ART, coinfection with HCV, and comorbidities such as diabetes, hypertension, and increased life expectancy—all may be contributing to the renal injury and dysfunction." (PMID 35720083, 2022). "A major strength of the NOD model for human T1D compared to diabetes induced by chemical substances (STZ, alloxan, dithizone) is the similarity to human T1D, as the NOD mice develop pancreatic islet β-cell autoantibodies and their islets are infiltrated with CD4+ and CD8+ lymphocytes." (PMID 36339443, 2022). "CD4+ T cells infiltrate in pancreatic islets with insulitis but no diabetes." (PMID 35498419, 2022). "However, in our study an increased proportion of Tregs in early onset NOD mice did not change diabetes incidence, despite a reduction in CD4+ T-cells and CD8+ T-cells in blood." (PMID 35296698, 2022).
diabetes (continued). "Additionally, most of the patients with type 2 diabetes mellitus have abnormal immune functions, such as decreased CD3+T and NK T cells, and imbalance of CD4+ /CD8+ T cells, which may aggravate SARS-CoV-2 infection." (PMID 36172213, 2022). "The authors noted a decrease in the PD-1 expression of CD4+ T lymphocytes in 12 T1DM patients as compared to healthy controls, highlighting that PD-1 might play a role in the development and/or maintenance of diabetes." (PMID 33672515, 2021). "While CD4+ T-cells are also present in the islets, they are not considered a major component of the immune infiltrate in established diabetes; this is not unexpected given the more prominent role of CD4+ T-cells in disease initiation rather than in disease progression/amplification." (PMID 33953728, 2021). "Others do not accelerate diabetes development (i.e. the CD4+ TCR BDC-2.5 reactive to a proinsulin/chromogranin-A hybrid peptide), unless on a NOD/scid immunodeficient background, and the CD8+ InsB15-23-reactive G9C8 TCR, which requires prior InsB15-23 immunisation)." (PMID 33084970, 2021). "In turn, the level of progression of diabetes is significantly influenced by the Treg subpopulation, the complexity and heterogeneity of which is confirmed by the detection of numerous tissue-specific Tregs, including the so-called VAT Tregs (visceral adipose tissue CD4+Foxp3+ regulatory T cells)." (PMID 32341701, 2020). "After diabetes manifestation, the islet infiltrate was composed of a high number of both immune cell types, CD8+ T cells and CD68 macrophages, and to a lesser extent of around 10 % CD4+ T cells as well as 10 % of NK-cells and B cells in the acutely diabetic rats." (PMID 32607871, 2020). "However, regardless of DQ type, people with diabetes had a higher frequency of proinflammatory ZnT8-specific CD4+ T cells than age- and HLA-matched non-diabetic individuals." (PMID 31444530, 2019). "Furthermore, Zbtb32 was preferentially induced in autoreactive CD4 T cells stimulated by these tolerogenic DCIR2+ DCs, and overexpression of Zbtb32 in islet-specific T cells inhibited the diabetes development by limiting T cell proliferation and cytokine production." (PMID 29707204, 2018). "The heterogeneity observed could be explained by WHO region, comorbid hypertension and diabetes mellitus, but not by gender, hepatitis B or C coinfection, CD4 count or antiretroviral status." (PMID 29659605, 2018). "When CD4+ T-cells were transferred in association with CD8+ T-cells from diseased ICOSL−/− NOD mice or even as a single subset into NOD.scid recipient mice, both recipient groups developed neuromyopathy but not diabetes." (PMID 28424681, 2017). "Regarding predictors, we found CRP and CD4 count were not predictors of pre-diabetes and diabetes." (PMID 28137307, 2017). "This study assessed the activation of CD4+ and CD8+ T-lymphocytes by human insulin and human glutamate decarboxylase (GAD) in patients with type 1 or type 2 diabetes mellitus (DM) and healthy volunteers." (PMID 28986401, 2017). "Similarly, CD4 count (used to assess severity of HIV because HIV viral loads were not routinely measured in Tanzania) was not a predictor of pre-diabetes and diabetes." (PMID 28137307, 2017). "However, HNT-CFP CD4+ T cells alone did not induce diabetes, predominantly remaining in a peri-insulitic disposition before clearance." (PMID 29403481, 2017). "A recent study of ACS with/without diabetes mellitus (DM) reported the highest frequencies of CD4+CD28− T cells when both conditions were present, followed by ACS only, DM only, and finally controls." (PMID 28303136, 2017). "However, depletion of CD4 T cells did not increase the magnitude of the CD8 T cell response or the incidence of diabetes generated by the TriVax boost." (PMID 29050282, 2017).